AHR (aryl hydrocarbon receptor)
Diseases named in the same sentence as AHR in open-access papers (continued):
Sharing a sentence is not in itself a finding about the gene and the disease.
diabetic nephropathy (15 papers, 2019 to 2025). "In a cohort of patients with diabetic nephropathy, higher AHR expression levels were found to be associated with more severe renal pathology and worse renal function." (PMID 37510393, 2023). "A previous study investigated the pathological role of AhR in diabetic nephropathy in in vitro and in vivo models, and revealed that AhR deficiency attenuates oxidative stress in both models." (PMID 36418969, 2022). "In addition to the changes in metabolic phenotype, diabetic nephropathy is also associated with increased apoptosis and increased mTOR, and possibly AhR, signaling." (PMID 39902076, 2024). "High AhR transactivating activity is an independent risk factor in diabetic nephropathy." (PMID 31488157, 2019). "Aryl hydrocarbon receptor (AhR), Short-chain fatty acids (SCFAs), Traditional Chinese medicine and soy milk provide researchers with treatment ideas for diabetic nephropathy." (PMID 40469726, 2025). "The data showed that the AhR mRNA level was increased in the kidneys of patients with diabetic nephropathy and CKD." (PMID 38940381, 2024). "AhR activity in patients with diabetes mellitus positively correlates with the progression of diabetic nephropathy and kidney failure severity." (PMID 35743162, 2022). "By culturing serum with an AHR reporter cell line, elevated AHR activity was identified in diabetic nephropathy patients compared to controls." (PMID 35237156, 2022). "It has been reported that serum AhR transactivating activity is higher in type 2 diabetic patients with diabetic nephropathy with microalbuminuria, macroalbuminuria and ESRD than in subjects with normoalbuminuria." (PMID 31488157, 2019). "Furthermore, in a murine model of diabetic nephropathy, AHR activation contributed to macrophage infiltration, extracellular matrix accumulation and mesangial cell activation." (PMID 37510393, 2023). "Moreover, AhR knockout mice, or pharmacological inhibition of the receptor with α-naphthoflavone (α-NF), also a partial agonist at the AhR, in diabetic nephropathy resulted in reduced oxidative stress." (PMID 35202128, 2022). "In this review, we summarize gut microbiota-derived ligands inducing AhR activity in patients with CKD, CVD, diabetic nephropathy and RCC that may provide a new diagnostic and prognostic approach for complex renal damage." (PMID 31488157, 2019). "For example, it has been demonstrated that patients with diabetic nephropathy showed elevated levels of serum AhR, which is further correlated to the increased levels of reactive oxygen species (ROS) and DNA damage, indicating the potential role of AhR in the pathogenesis of diabetic nephropathy." (PMID 36418969, 2022). "AhR activation was found to increase the expression of COX-2, whereas in the AhR knockout mice model of diabetic nephropathy, COX-2 activity and PG production was significantly lower, together with decreased lipid peroxidation, oxidative stress level, and extracellular matrix accumulation." (PMID 36788192, 2023).
Glucose intolerance (15 papers, 2016 to 2025). Glucose intolerance (GI) can be defined as dysglycemia that comprises both prediabetes and diabetes. "Collectively, these animal studies suggest a possible role of AhR/CYP1 activation in glucose intolerance, impaired insulin secretion, pancreatic islet dysfunction, and, consequently, the development of DM." (PMID 40408591, 2025). "TCDD exposure is well known to reorganize AhR target gene expression as well as other pro-inflammatory pathways in the liver to promote glucose intolerance and other related metabolic disturbances." (PMID 35448550, 2022). "Surprisingly, we observed that AhR−/− mice exhibited lower fasting glucose levels and improved glucose tolerance, compared with AhR+/+ mice indicating partial protection against diet-induced glucose intolerance in AhR−/− mice." (PMID 28721249, 2016). "Interestingly, administration of an AhR antagonist prevented glucose intolerance in DL-PCB-exposed mice, confirming that DL-PCBs exert their effects through AhR." (PMID 35156417, 2022). "However, we did observe that the AhR−/− mice were partially protected against diet-induced glucose intolerance." (PMID 28721249, 2016). "Interestingly, exposing AhR−/− mice to a high-fat diet showed resilience to glucose intolerance." (PMID 28721249, 2016). "However, with dietary challenge the AhR−/− mice is probably more efficient in disposal of glucose load to peripheral tissues as well as restricting gluconeogenesis, preventing HFD induced glucose intolerance." (PMID 28721249, 2016). "However, the precise mechanisms linking the AhR/CYP1 pathways, epigenetic modifications, and glucose intolerance remain unclear." (PMID 40408591, 2025).
influenza (15 papers, 2016 to 2025). An acute viral infection of the respiratory tract, occurring in isolated cases, in epidemics, or in pandemics; it is caused by serologically different strains of viruses (influenzaviruses) designated A, B, and C, has a 3-day incubation period, and usually lasts for 3 to 10 days. "Loss of the endothelial aryl hydrocarbon receptor (AHR) also increases tissue barrier dysfunction and subsequent movement of inflammatory cells into alveoli following influenza infection." (PMID 38686182, 2024). "Failure to induce expression of IL22 following influenza infection was associated with inefficient activation of AhR." (PMID 34906172, 2021). "Additionally, animal studies have found that transplacental exposures to chemicals that bind to and activate the aryl hydrocarbon receptor (AHR) adversely affect later-life immune effects by decreasing the immune response to influenza and by increasing autoimmune susceptibility in adults." (PMID 26495820, 2016). "Since CYP1 enzymes are negative regulators of AHR activation, the authors generated a Cyp1-deficit mouse to investigate uninterrupted expression and signaling of endothelial AHR during influenza infection." (PMID 38388453, 2024). "In parallel, we profiled the transcriptome of lung epithelial cells (EpCam+) in naïve and influenza infected WT and ECΔAhr mice to understand indirect consequences of disrupted endothelial AHR signalling." (PMID 37587341, 2023). "Taken together, these findings identify the apelin/APLNR signalling axis as a mechanism of AHR-dependent lung protection, preventing endothelial stress, vascular leakage, and epithelial remodelling, upon influenza-induced lung damage." (PMID 37587341, 2023). "A highly consistent feature in our influenza model was the marked depression of AHR signalling in WT lung endothelial cells upon infection." (PMID 37587341, 2023). "Here we show that the environmental sensor aryl hydrocarbon receptor (AHR) is highly active in lung endothelial cells and protects against influenza-induced lung vascular leakage." (PMID 37587341, 2023). "Only OVA-challenged mice that had the additional insult of influenza infection displayed AHR (relative to those challenged with saline or HDM, or mock-infected mice)." (PMID 34445491, 2021). "We determined the expression of Cyp1a1, a marker for AhR activation, in PM-exposed and influenza-infected mice." (PMID 34906172, 2021). "Significant involvement of AhR-signaling in immunity is established for infection with e.g., influenza and toxoplasma." (PMID 31749794, 2019). "On the contrary, a recent study demonstrated that selectively reducing AhR expression in the lung endothelium protected against influenza-induced pathology, highlighting that the tissue-protective function of AhR plays a dual role at different stages of the disease." (PMID 40863240, 2025). "However, amplified lung AHR signalling induced by dietary ligands protected mice against influenza-induced tissue damage and vascular leakage." (PMID 37587341, 2023). "Together, these results suggest an association between suppressed IL22 expression and altered AhR activation and indicate that failure of AhR activation may have led to suppressed IL22 expression following influenza infection." (PMID 34906172, 2021). "Moreover, AHR activation is known to increase the number of neutrophils recruited to infected tissues, such as lung airways during influenza infection." (PMID 31083300, 2019). "Of note, several Trp metabolites produced by bacteria in the gut are endogenous ligands for the transcription factor aryl hydrocarbon receptor (AhR) which has been recently shown to control B-cell fate decisions including suppression of class switching in vivo after influenza immunization." (PMID 28893288, 2017).
influenza (continued). "We were also interested in whether the two xenosensors, NRF2 and AHR (representing known targets of tBHQ in hepatocytes and other cell types), were involved in the regulation of genes of significance in influenza and SARS-CoV-2 infection after chronic exposure to this food additive." (PMID 35629310, 2022). "Furthermore, AhR is suggested to be a suppressor of lung inflammation through its interaction with nuclear factor-κB as has been shown in studies evaluating cigarette smoke or influenza." (PMID 27567616, 2016).
periodontitis (15 papers, 2019 to 2025). An acute or chronic inflammatory process that affects the tissues that surround and support the teeth. "The researchers observed significantly elevated levels of AHR and interleukin-22 (IL-22) in patients with periodontitis, which were found to be associated with osteoclast resorptive activity and disease severity." (PMID 39575260, 2024). "The protective effects of 6-Formylindolo[3,2-b]carbazole (FICZ) and the aryl hydrocarbon receptor signaling pathway on alveolar bone loss and inflammation have been recently discussed in the context of experimental periodontitis." (PMID 34776994, 2021). "Oral administration of P. gingivalis in mice alters tryptophan metabolism, increasing serum kynurenine as a direct precursor of KYNA while reducing fecal and serum AhR activities, in consistence with blood kynurenine and tryptophan metabolism as causal risks for periodontitis." (PMID 39227984, 2024). "Meanwhile, research observations suggest that the AHR pathway may play a significant role in systemic diseases associated with periodontitis." (PMID 39575260, 2024). "Given smoking is also an important risk factor for periodontitis, it is postulated that the exogenous activation of AHR may play an important role in the onset and progression of both conditions." (PMID 39575260, 2024). "Over the past few years, the scholarly inquiry into AHR has progressively broadened to encompass its implications in the pathogenesis of periodontitis and the development of therapeutic interventions." (PMID 39575260, 2024). "Additional research is warranted to investigate the function and mechanism of the AHR in host-microbial interactions in periodontitis." (PMID 39575260, 2024). "The expression of AHR is markedly reduced in inflamed gingival tissue of C57BL/6 mice with experimental periodontitis and in an in vitro inflammation model using RAW 264.7 macrophage cells." (PMID 39575260, 2024). "The findings of another study indicated that activation of the AHR contributed to the mitigation of periodontitis and modulated the AHR/NF-κB/NLRP3 inflammasome pathway in a mouse model." (PMID 39575260, 2024). "This review will specifically examine the impact of AHR on periodontal homeostasis in the context of periodontitis and related systemic disorders." (PMID 39575260, 2024). "This review concentrates on the modulation of the AHR pathway and the intricate functions that AHR plays in periodontitis." (PMID 39575260, 2024). "There exist multiple AHR ligands within the oral cavity that have the potential to induce aberrant AHR expression in the context of periodontitis." (PMID 39575260, 2024). "Studies have shown that endogenous ligand-activated AhR suppresses NF-κB signaling periodontitis and IBD." (PMID 39416781, 2024). "A study has highlighted the disruptive impact of periodontitis-related pathogens, such as Porphyromonas gingivalis, and their byproducts on the host’s immune equilibrium, with the AHR potentially serving as a specific mechanism linking these processes." (PMID 39575260, 2024). "It has been demonstrated that AHR activation can modulate the inflammation and immune response in periodontitis by impacting immune cells and inflammatory factors." (PMID 39575260, 2024). "In order to elucidate the mechanism of P. gingivalis on AhR in the pathogenesis of periodontitis, the effect of P. gingivalis on AhR signalling was determined in RAW 264.7 cells." (PMID 36446468, 2023). "The schematic figure illustrating P. gingivalis inhibits Aryl hydrocarbon receptor (AhR) signalling pathway in periodontitis." (PMID 36446468, 2023). "To figure out the role of P. gingivalis on AhR signalling pathway in periodontitis, we analysed the related inflammatory factors in P. gingivalis inoculated experimental periodontitis mice and investigate the potential mechanism using RAW 264.7 cells." (PMID 36446468, 2023).
periodontitis (continued). "In C57BL/6 wild-type mice with experimental periodontitis, calcitriol intervention enhances Aryl hydrocarbon receptor (AhR) signaling, which further restrains the activation of NF-κB signaling pathway in gingival epithelium." (PMID 36359775, 2022). "This study aimed to explore the effect of VD3 treatment on periodontitis and AhR/NF-κB/NLRP3 inflammasome pathway in the gingival epithelium of C57BL/6 wild-type mice with experimental periodontitis induced by P. gingivalis inoculation." (PMID 31691738, 2019). "Moreover, the AHR also plays a regulatory role in innate immune cells, particularly macrophages, which play a crucial role in the immune response and inflammation in periodontitis." (PMID 39575260, 2024). "This implies the potential role of AHR in modulating the inflammatory milieu of the oral microenvironment in periodontitis, necessitating further experimentation to substantiate its impact and elucidate its underlying mechanism in the context of periodontal disease." (PMID 39575260, 2024). "The strategic activation of the AHR pathway may represent a shared therapeutic approach for both periodontitis and AD." (PMID 39575260, 2024). "Given the strong correlation between smoking and periodontitis, it is plausible that the AHR may exhibit heightened expression in the oral cavity of individuals who smoke and have periodontitis." (PMID 39575260, 2024). "It is concluded that P. gingivalis may promote inflammatory responses via inhibiting the AhR signalling pathway in periodontitis." (PMID 36446468, 2023). "AhR signalling pathway is significantly suppressed in periodontitis." (PMID 36446468, 2023). "Overall, this study provides evidence supporting perhaps a novel mechanism by which P. gingivalis could induce inflammatory responses in periodontitis by suppressing the AhR signalling pathway." (PMID 36446468, 2023). "In this study, it is demonstrated that P. gingivalis may regulate AhR signalling in periodontitis, which provides a potential target for further immune regulation studies in periodontitis." (PMID 36446468, 2023). "The crosstalk between AhR signaling and NF-κB/NLRP-3 inflammasome pathway might be the underlying mechanism of therapeutic efficacy of vitamin D on periodontitis-related bone loss." (PMID 36359775, 2022). "The protective VD3 effect on periodontitis may correlate with the regulation of AhR/NF-κB/NLRP3 inflammasome pathway." (PMID 31691738, 2019). "Hence, the potential linkage between periodontitis and RA may be attributed to the aberrant activation of AHR signaling pathways." (PMID 39575260, 2024). "The dysbacteriosis in periodontitis may influence the development of AD through AHR signaling." (PMID 39575260, 2024). "However, whether P. gingivalis infection affects inflammation and immune imbalance via regulating the AhR signalling in periodontitis remains unclear and demands further investigation." (PMID 36446468, 2023). "Since it was recently suggested that Th22 lymphocytes could be associated with the RANKL-mediated alveolar bone loss in a mice model of A. actinomycetemcomitans-induced experimental periodontitis, we also compared the infiltration of AhR+ T lymphocytes within the periodontal lesions." (PMID 33193431, 2020). "The aryl hydrocarbon receptor (AHR), a ligand-activated transcription factor, plays a crucial role in the pathogenesis of periodontitis." (PMID 39575260, 2024). "P. gingivalis infection suppressed AhR and its downstream indoleamine 2,3‐dioxygenase (IDO) expression in periodontitis, which is responsible for the degradation of tryptophan (Trp) to kynurenine (Kyn)." (PMID 36446468, 2023). "The current report showed that P. gingivalis infection suppressed AhR and its downstream IDO expression in periodontitis, which is responsible for the degradation of Trp to Kyn." (PMID 36446468, 2023). "In the present study, AhR and its direct targets CYP1A1 and CYP1B1 were reduced in P. gingivalis‐infected experimental periodontitis mice model." (PMID 36446468, 2023).
periodontitis (continued). "Research indicates elevated expression of AHR in individuals with periodontitis compared to those without the condition." (PMID 39575260, 2024). "Similarly, gene expression of AhR, CYP1A1, CYP1B1, and IDO analysed by qRT‐PCR were also decreased in periodontitis mice." (PMID 36446468, 2023). "During the inflammatory response of periodontitis, the lymphocytes, macrophage and neutrophils are regulated by expression of multiple genes, such as ARHGAP10, ARPC1B, DOCK1, FGF2/4, TNFRSF1B, NXT1, and AHR, all of which were identified in our analysis." (PMID 35491409, 2022). "In addition, we found that the expression of AhR and its downstream CYP1A1 was upregulated in gingival epithelia in periodontitis mice compared with their normal controls." (PMID 31691738, 2019).